CCR7 (C-C motif chemokine receptor 7)
Description:
Receptor for the MIP-3-beta chemokine. Probable mediator of EBV effects on B-lymphocytes or of normal lymphocyte functions.
Synonyms: CC-CKR-7; CCR-7; EBI1; CD197; CMKBR7; BLR2; CDw197
Tractability: Small molecule: a structure with a bound ligand is known; it belongs to a druggable protein family. Antibody: its Gene Ontology location is reachable by antibodies, with high confidence; UniProt places it where antibodies can reach, with medium confidence; UniProt predicts a signal peptide or a membrane-spanning region. PROTAC: ubiquitination databases record sites on it; its protein half-life has been measured; a small molecule that binds it is known.
Target class: Chemokine receptor; Peptide receptor (family A GPCR); Family A G protein-coupled receptor; CC chemokine receptor; Membrane receptor
Gene: Protein-coding gene on chromosome 17 (40,551,081 to 40,565,472, reverse strand). Ensembl gene ENSG00000126353.
Subcellular location: Cell membrane
Subcellular location (Human Protein Atlas): Mitochondria
Pathways (Reactome):
Signal Transduction: Chemokine receptors bind chemokines; G alpha (i) signalling events
Gene Ontology:
Molecular function: C-C motif chemokine 19 receptor activity; C-C motif chemokine 21 receptor activity; chemokine (C-C motif) ligand 19 binding; chemokine (C-C motif) ligand 21 binding; protein binding; C-C chemokine receptor activity; G protein-coupled receptor activity; chemokine receptor activity
Biological process: CCL19-activated CCR7 signaling pathway; CCL21-activated CCR7 signaling pathway; cellular response to cytokine stimulus; cellular response to prostaglandin E stimulus; myeloid dendritic cell chemotaxis; positive regulation of neutrophil chemotaxis; positive regulation of phosphatidylinositol 3-kinase/protein kinase B signal transduction; positive regulation of phospholipase C/protein kinase C signal transduction; release of sequestered calcium ion into cytosol; calcium-mediated signaling; cell chemotaxis; dendritic cell chemotaxis; establishment of T cell polarity; G protein-coupled receptor signaling pathway; immune response; inflammatory response; lymphocyte migration into lymph node; mature conventional dendritic cell differentiation; negative regulation of dendritic cell apoptotic process; negative regulation of interleukin-12 production; positive regulation of actin filament polymerization; positive regulation of canonical NF-kappaB signal transduction; positive regulation of cell adhesion; positive regulation of cell motility; positive regulation of cell-matrix adhesion; and 24 more
Cellular component: cell surface; mitochondrion; plasma membrane; external side of plasma membrane; membrane
Genetic constraint (gnomAD): Loss-of-function variants: 11 observed, 27.59 expected, observed/expected ratio (o/e) 0.4, 90% interval 0.25 to 0.66. The upper end of that interval is the gene's LOEUF score, 0.66, which puts it in group 2 of 6, group 1 being the genes least tolerant of losing a copy. Missense variants: 360 observed, 529.73 expected, observed/expected ratio (o/e) 0.68, 90% interval 0.62 to 0.74. Synonymous variants: 189 observed, 213.87 expected, observed/expected ratio (o/e) 0.88, 90% interval 0.78 to 1.
Homologues: Orthologues: chimpanzee CCR7 (99% identical), macaque CCR7 (99% identical), pig CCR7 (92% identical), dog CCR7 (91% identical), rabbit CCR7 (91% identical), mouse Ccr7 (87% identical), rat Ccr7 (86% identical), guinea pig CCR7 (84% identical), tropical clawed frog ccr7 (55% identical), zebrafish ccr7 (48% identical). Paralogues in human: CCR9 (39% identical), CCR6 (38% identical), CCR10 (36% identical), ACKR4 (34% identical), CCR2 (32% identical), CCR4 (32% identical), CXCR2 (32% identical), CXCR5 (32% identical), CCR1 (31% identical), CCR5 (31% identical), CXCR3 (31% identical), CX3CR1 (30% identical), and 11 more.
Diseases named in the same sentence as CCR7 in open-access papers:
CCR7 is named in the same sentence as 362 diseases in open-access papers, as found by Europe PMC text mining. Sharing a sentence is not in itself a finding about the gene and the disease. The quoted sentences say what the papers report.
breast cancer (138 papers, 2006 to 2026). A primary or metastatic malignant neoplasm involving the breast. "For example, in breast cancer, CCR7 is highly expressed in tumor cells and metastatic sites, and CCR7/CCL21 signaling is associated with lymph node metastasis and tumor progression." (PMID 40038879, 2025). "In this meta-analysis, a total of 12 studies exploring the association between CCR7 expression and the clinicopathological features of breast cancer patients were evaluated." (PMID 40299690, 2025). "Studies have shown that elevated CCR7 expression levels are associated with lymph node metastasis in a variety of tumors (including breast cancer, esophageal cancer, cervical cancer, thyroid cancer, lung cancer and oral squamous cell carcinoma)." (PMID 38539232, 2024). "TAK1 expression is commonly elevated in breast cancer tissue and often linked to elevated levels of CCR7 expression." (PMID 35203305, 2022). "Again, results are not necessarily one sided since CCR7 gene mutations can be beneficial in cancer since, in breast cancer samples, CCR7 splice variants increased patient survival." (PMID 35203305, 2022). "HER2/neu (Chr17q12-21) and CCR7 are located close together on chromosome 17 and CCR7 is co-amplified with HER2/neu in approximately 20% of cases, although approximately 4% of HER2 amplified breast cancer samples were associated with CCR7 genomic deletion." (PMID 35203305, 2022). "Using a similar MMTV-PyMT-driven mouse model, a second study reported that CCR7 deletion delayed mammary tumor formation, likely via the loss of stem-like cells." (PMID 35203305, 2022). "Chemokine receptors CXCR4 and CCR7 have been shown to be linked to the metastatic spread of breast cancer, however, their precise function and underlying molecular pathways leading to the acquisition of the pro-metastatic properties remain poorly understood." (PMID 34685420, 2021). "We first validated the PLA approach for the detection of endogenous CXCR4 and CCR7 association in breast cancer cells lines, differing in their invasive phenotype." (PMID 34685420, 2021). "CCR7 over-expression is associated with larger primary tumors, deeper lymphatic invasion and poorer survival rates in breast cancer." (PMID 31555130, 2019). "The present study aimed to determine the CCR7 marker expression and its association with clinicopathologic characteristics using immunohistochemistry method in patients with breast cancer referred to Imam Khomeini Hospital, Sari, Iran between 2011 and 2016." (PMID 30233771, 2018). "The aims of our study were to explore the effect of CCR7 on the EMT of breast cancer cells and the underlying mechanisms." (PMID 28378417, 2017). "Pan and colleagues reported that TAK1 activation is associated with increased CCR7 expression in breast cancer cells." (PMID 28858212, 2017). "In the search for mechanistic clues of the CCR7-mediated augmentation of the mammary stem cell compartment, we investigated crosstalk between CCR7 and Notch1 pathways, as Notch1 signaling has also been implicated in mammary cancer stem cells." (PMID 28137279, 2017). "We have shown that a molecular cross-talk between breast cancer cells and LEC via the CCL21/CCR7 chemokine/ chemokine receptor axis plays a major role in breast cancer associated lymphangiogenesis." (PMID 28056899, 2017). "Given the recent evidence suggesting the implication of C-C chemokine ligand 21/chemokine receptor 7 (CCL21/CCR7) in lymph node metastasis, the aim of our study was to define the role of this chemokine pair in breast cancer-associated lymphangiogenesis." (PMID 25744065, 2015). "Because the CCL21/CCR7 axis has been associated with lymph node metastasis of breast cancer (for review see:) cell migration studies were conducted by using the 3D-collagen matrix migration assay." (PMID 23667660, 2013). "Additionally, CCR7 expression is significantly correlated with advanced tumor stage and lymph-node metastasis in breast cancer patients and is associated with a poor prognosis." (PMID 40299690, 2025).
breast cancer (continued). "CCR7 was selected as the focus of this study due to its previously reported associations with poor overall survival, advanced tumor stage, and lymph-node metastasis in breast cancer patients, as highlighted in the introduction." (PMID 40299690, 2025). "Taken together, while these studies demonstrate that CCR7 seems to reliably predict the presence of lymph node metastases in more aggressive breast tumors, it is unclear whether CCR7 can be linked to patient survival in all breast cancers." (PMID 35203305, 2022). "In breast cancer, CCR7 expression was significantly associated with COX-2 expression (p = 0.008)." (PMID 35203305, 2022). "CCR7 has also been linked to the formation of a new lymphoid vessel in breast carcinoma patient samples, but the actual mechanism is still unknown." (PMID 35874608, 2022). "Chemokine receptor CCR7 is implicated in the metastasis of breast cancer to the lymph nodes." (PMID 34298676, 2021). "Moreover, anti‐activation of the PI3K/AKT pathway in CCR7‐knockdown breast cancer cells causes of decreased N‐cadherin expression." (PMID 28378417, 2017). "Our study adds new elements to the multifaceted role of CCL21/CCR7 chemokine pair in mammary malignancy by revealing a novel role of this chemokine axis in breast cancer-associated lymphangiogenesis that might be relevant to future therapies." (PMID 25744065, 2015). "Because the CCL21/CCR7 axis has been linked to metastatic spreading of breast cancer to lymph nodes we conclude from our data that cell fusion could be a mechanism explaining the origin of metastatic cancer (hybrid) cells." (PMID 23667660, 2013). "Because the CCL21/CCR7 axis has been associated with lymph node metastasis formation of breast cancer we conclude that cell fusion between breast cancer cells and breast epithelial cells exhibiting stem cell properties is a possible mechanism how metastatic cancer hybrid cells can originate." (PMID 23667660, 2013). "Collectively, the data suggest that the zebrafish embryo model can be used to monitor the migration of breast cancer cells in a living animal, and let-7a overexpression or CCR7 silencing could cause a significant reduction in breast cancer cell migration in vivo." (PMID 22251626, 2012). "In breast malignant tumor cells, actin polymerization and filopodia are mediated by C‐C chemokine receptor 7 (CCR7) or C‐X‐C chemokine receptor type 4 (CXCR4) signaling, which subsequently induces chemotactic and invasive responses." (PMID 39957375, 2025). "CCR7 has been shown to form heterodimers with CXCR4 in breast cancer cells resulting in a metastatic phenotype as well as allowing for increased survival in the absence of an extracellular matrix (ECM) attachment." (PMID 39982274, 2025). "Our meta-analysis examined the relationship between CCR7 expression and various outcomes of interest in breast cancer patients." (PMID 40299690, 2025). "Background/Objective: This study aimed to determine the clinicopathological findings and prognostic value of chemokine receptor 7 (CCR7) expression in patients with breast cancer (BC)." (PMID 40299690, 2025). "Nonetheless, large, high-quality, prospective studies are essential to confirm these findings, address heterogeneity, and better evaluate CCR7 expression’s role in breast cancer." (PMID 40299690, 2025). "While direct mechanistic evidence for CCR7 recruiting Tregs in breast cancer is limited, CCR7’s role in lymphatic migration and immune cell homing suggests a plausible link to immunosuppression." (PMID 41462979, 2025). "Research has also shown that there is a decrease in the quantity of peripheral DCs in patients with breast cancer, accompanied by a reduction in the expression levels of surface chemokine receptors like CCR7." (PMID 40333202, 2025). "The lack of detailed subtype information further limited our ability to perform subgroup analyses, restricting insights into CCR7’s role across different breast cancer contexts." (PMID 40299690, 2025).
breast cancer (continued). "Silencing CCR7 in metastatic breast cancer cell lines has been shown to reduce motility, migration, and invasion both in vitro and in vivo." (PMID 39982274, 2025). "The CCR7-CCL19 and CCR7-CCL21 axes have been shown to promote lymph node metastasis in CCR7-expressing breast cancer cells." (PMID 40028039, 2025). "CCR7 is often up-regulated together with CXCR4 in cancer and is associated with lymph node metastases in breast cancer." (PMID 39001456, 2024). "In an analysis of the TCGA database, mRNA relative expression levels of GZMK (log2(TPM + 1)) were correlated with CTLA4, PD-1, PD-L1, CD48, and CCR7 in patients with breast cancer." (PMID 38833021, 2024). "There are few reports on the significance of CCR7 expression on human breast cancer cells by immunohistochemistry." (PMID 39001456, 2024). "Among all known chemokine receptors, chemokine receptor 4 (CXCR4) and chemokine receptor 7 (CCR7) display a relatively high expression in breast malignant tumors and metastatic tissues." (PMID 38549934, 2024). "The promotion of cancer cell migration into micro lymphatic capillaries by CCL21/CCR7 has also been observed in breast cancer and esophageal squamous cell carcinoma." (PMID 36829431, 2023). "Recently, we reported that TGFβ1 stimulated breast cancer cells with mesenchymal properties to migrate in a targeted fashion towards the lymphatic system via CCR7/CCL21-mediated chemotaxis, similar to dendritic cells during inflammation." (PMID 38055067, 2023). "Previously, we reported that TGFβ1-induced EMT promotes lymphatic dissemination of breast cancer cells by activating CCL21/CCR7-mediated chemotaxis." (PMID 38055067, 2023). "This pathway hinges on the binding of CCL19 to its receptor, CCR7, expressed on the surfaces of breast cancer cells." (PMID 37944262, 2023). "As a seven-fold transmembrane GPCR, chemokine receptor 7 (CCR7) is expressed by a variety of tumor types, including breast cancer, gastric carcinoma, and colorectal cancer." (PMID 36829431, 2023). "The CCL19/CCR7 pathway emerges as a pivotal player in breast cancer, notably in the context of lymph node metastasis, and orchestrates a series of intricate molecular mechanisms." (PMID 37944262, 2023). "For instance, CXCL13 elevation was related to a poor prognosis in breast cancer, and CCR7 upregulation in some cancer cells enhanced lymph node metastasis." (PMID 36890557, 2023). "To further explore the effect of CCR7 on breast cancer cells, we transfected MCF-7 and MDA-MB-231 cells using siCCR7." (PMID 37864213, 2023). "Based on the fact that CCR7/CCL19 plays a crucial role in breast cancer development and metastasis, we further explored the IncRNAs and micRNAs associated with it and constructed a ceRNA network." (PMID 37864213, 2023). "During the development of breast cancer, there exists a potential link between endothelins and CCR7." (PMID 35203305, 2022). "In most forms of breast cancer, expression of CCR7 correlates with decreased 5 year survival and tumor recurrence." (PMID 35203305, 2022). "Like what was observed in breast cancer, expression of CCR7 in colon cancer can elevate the EMT markers." (PMID 35203305, 2022). "More importantly, CCL19/CCR7-induced breast cancer cell growth was found to be significantly repressed and anoikis increased when cells were treated with sialyltransferase inhibitors." (PMID 35203305, 2022). "Expression of VEGF-C and CCR7 were reported in human breast cancer tissue, leading to the promotion of lymphatic invasion." (PMID 35203305, 2022). "This was in line with our observation that in a murine model, breast cancers that were metastatic to the lung also had reduced lung metastases in the presence of CCR7." (PMID 35203305, 2022). "In vitro studies showed that HIF-1, which is induced under low oxygen tension, increased the expression of CCR7 in breast cancer, ovarian epithelial and head and neck cancer cells." (PMID 35203305, 2022).
breast cancer (continued). "At diagnosis, the correlation between CCR7 expression and lymph node metastasis appears to be complex in breast cancer." (PMID 35203305, 2022). "It will be important to examine the anti-breast cancer immune responses in women with CCR7(+) metastases within the lymph nodes." (PMID 35203305, 2022). "In contrast, more aggressive luminal B breast cancers had high CCR7 expression levels, which correlated well with lymph node metastasis." (PMID 35203305, 2022). "A family member, miR-let-7a, reduces breast cancer migration/invasion by downregulating CCR7 expression." (PMID 35203305, 2022). "The results suggest that miR-335 upregulated CCR7 expression and miR-let-7a has opposite effects, such as its effects on CCR7 in breast cancer tissue." (PMID 35203305, 2022). "C-C chemokine receptor 7 (CCR7) was one of the first two chemokine receptors that were found to be upregulated in breast cancers." (PMID 35203305, 2022). "Elevated COX-2 in breast cancer cells led to increased CCR7 and enhanced migration of breast cancer cells to lymphatic endothelial cells and lymph node metastasis." (PMID 35203305, 2022). "Initial studies reported that CCR7 mRNA levels were elevated in seven human breast cancer cell lines when compared to normal primary mammary epithelial isolates." (PMID 35203305, 2022). "Clearly, in breast cancer, signaling through CCR7 can have different outcomes dependent upon the state of the cancer." (PMID 35203305, 2022). "Previous studies postulated that CCR7 is abnormally upregulated in a number of malignancies such as breast cancer, lung adenocarcinoma and gastric cancer." (PMID 35904690, 2022). "Increased VEGF-C and CCR7 expression in breast carcinoma tissue and increased CCL21/CCR7 activation in lymphatic endothelial cells promoted lymphatic endothelial cell proliferation and lymph node metastasis of the CCR7-expressing breast cancer cells." (PMID 35203305, 2022). "Like breast cancer, CCR7 was upregulated by COX-2 activity in colon cancer as well, although the correlation with cancer progression was undetermined." (PMID 35203305, 2022). "This TGF-β1-mediated lymphatic migration was associated with CCL21 release from lymphatic endothelial cells and chemotaxis of CCR7-expressing breast cancer cells." (PMID 35203305, 2022). "In breast cancer, miR-let-7a did indeed reduce CCR7 levels with concomitant attenuation of breast cancer cell migration and invasion." (PMID 35203305, 2022). "This correlation was even more evident in highly aggressive triple-negative breast cancers, where CCR7 was highly expressed in both cell lines and breast cancer tissue." (PMID 35203305, 2022). "For example, in breast cancer, let-7a suppresses the expression of CCR7 and reduces the ability of cancer cells to migrate and invade." (PMID 36243683, 2022). "We found that the expression of CCR7 in breast cancer was mostly nuclear in lobular carcinoma and cytoplasmic in ductal carcinoma, with cytoplasmic staining being more prevalent." (PMID 34298676, 2021). "We also established a direct connection between the activation of CXCR4 and CCR7, and the inhibition of detachment-induced apoptosis (anoikis) in metastatic breast cancer cells that potentially contributes to the metastatic spread of mammary tumours." (PMID 34685420, 2021). "We observed dose-dependent cAMP inhibition after the stimulation of cells with either ligand, demonstrating that CXCR4 and CCR7 are functionally active in advanced human breast cancer cells." (PMID 34685420, 2021). "We found that CCL21/CCR7 expression by breast cancer cells promoted tumor-induced lympho-vascular recruitment in vivo and VEGF-C production by LECs in vitro." (PMID 33668160, 2021). "Chemokine receptor CCR7 and its ligand CCL21 are implicated in the metastasis of breast cancer to the lymph nodes." (PMID 34298676, 2021).